CCAT2 (colon cancer associated transcript 2)
Diseases named in the same sentence as CCAT2 in open-access papers (continued):
Sharing a sentence is not in itself a finding about the gene and the disease.
glioma (continued). "And 58.2% (78 out of 134) glioma tissue samples showed high expression of CCAT2 mRNA compared with that adjacent normal tissues, while 11.9% (16 out of 134) tissues showed no change." (PMID 27833083, 2016). "We found that expression of CCAT2 was up-regulated in glioma tissues and significantly correlated with the advanced tumor stage (III/IV)." (PMID 27833083, 2016). "To further understand the biological function of CCAT2 in glioma, we performed a series of functional assays." (PMID 27833083, 2016). "Having found the effect of CCAT2 downregulation on the proliferation of glioma cell lines, we then examined the impact of decreased expression of CCAT2 on cell cycle in glioma cells." (PMID 27833083, 2016). "To investigate the potential biological functions of CCAT2 in glioma, we evaluated the CCAT2 mRNA expression by qRT-PCR in paired glioma tissues and adjacent normal tissues obtained from 134 patients with glioma." (PMID 27833083, 2016). "To further explore the specific mechanism regulated by CCAT2 in the proliferation of glioma cells, we tested the effect of CCAT2 on Wnt/β-catenin signaling using a reporter LEF/TCF promoter dual-luciferase construct." (PMID 27833083, 2016). "Consist with previous results; β-catenin expression in nuclei was remarkedly decreased when the CCAT2 was knocked down using shRNA construct in the glioma cells cells." (PMID 27833083, 2016). "Further, levels of CCAT2 in nuclear and cytoplasmic fractionated U87-MG and U251 cells revealed that CCAT2 was mainly existed in the nucleus of glioma cells (more than 65%)." (PMID 27833083, 2016). "In the current study, we used quantitative real-time PCR (qRT-PCR) to determine the expression of CCAT2 in glioma tissues." (PMID 27833083, 2016). "In the current study, we found that CCAT2 was upregulated in glioma tissues compared to matched adjacent tissues." (PMID 27833083, 2016). "In the present study, we found that CCAT2 was abundantly expressed in glioma tissues and positively correlated with advanced tumor stage." (PMID 27833083, 2016). "Further analysis indicated the effect of CCAT2 knockdown on glioma cell phenotype through inhibiting Wnt/β-catenin signal pathway activity." (PMID 27833083, 2016). "U87-MG and U251 cells were seeded in 6-well plates, and the specific lentiviral vector expressing CCAT2 shRNAs was transected to glioma cell lines to determine its effect on the proliferation of glioma cells in vitro." (PMID 27833083, 2016). "Similar efficiency of cellular growth behaviors of glioma was also observed in vivo that the CCAT2 knockdown decreased tumor formation." (PMID 27833083, 2016). "In this study, we explored the expression pattern of CCAT2 in glioma patients and its correlation with clinicopathological factors of glioma." (PMID 27833083, 2016). "For example, a study investigating the impact of glioma cells on angiogenesis found that glioma cells could enhance this process by delivering Linc-CCAT2 to endothelial cells via exosomes." (PMID 38398214, 2024). "For instance, it has been demonstrated that glioma cells might stimulate angiogenesis by transferring linc-CCAT2 and linc-POU3F3 to endothelial cells through exosomes." (PMID 35448031, 2022). "The silencing of CCAT2 attenuates the proliferation, cell cycle, and migration of glioma cells." (PMID 34499007, 2021). "It was demonstrated that lncRNA CCAT2 may promote glioma progression, cell proliferation and endothelial angiogenesis by inducing the PI3K/AKT signaling pathway." (PMID 34200145, 2021). "Similarly, knockdown of CCAT2 suppresses cell migration, proliferation, cell cycle progression, and tumorigenesis in glioma by downregulating the Wnt/β-catenin signaling pathway." (PMID 33980320, 2021). "A high level of CCAT2 in gliomas is predictive of poor clinical results." (PMID 34499007, 2021).
glioma (continued). "For instance, a study that aimed to determine the processes of the glioma cell–affected angiogenesis noted that glioma cells might stimulate angiogenesis by transferring Linc-CCAT2 to endothelial cells through exosomes." (PMID 34722277, 2021). "CCAT2-enriched exosomes are also released by glioma cells and may also be involved in human umbilical vein endothelial cells." (PMID 33980320, 2021). "Therefore, the release of exosomes containing the lncRNA CCAT2 by glioma cells promotes angiogenesis and inhibits endothelial cell apoptosis." (PMID 33980320, 2021). "Similarly, the extracellular export was documented for the long intergenic non-coding RNA (lincRNA) known as CCAT2 (linc-CCAT2) and frequently upregulated in glioma cells." (PMID 30585246, 2018). "Knockdown CCAT2 expression decreased glioma cell growth, migration and invasion." (PMID 29502343, 2018). "Indeed, knockdown of CCAT2 inhibited glioma cell proliferation and migration by repressing the Wnt/β-catenin pathway." (PMID 28187439, 2017). "Moreover, previous studies have found that CCAT2 is related with many tumor types such as glioma, gastric cancer, bladder cancer, and small cell lung cancer." (PMID 28108736, 2017). "Additionally, the mRNA levels and protein expression levels of c-Myc, MMP-7 and cyclinD1 were significantly decreased in stable expression glioma cells with CCAT2 shRNA." (PMID 27833083, 2016). "CCAT2 expression offers insight into a potential biomarker for diagnosis in glioma patients." (PMID 27833083, 2016). "In addition, to strengthen tissue expression analysis, we enrolled another 56 paired glioma tissues and adjacent normal tissues to confirm the expression level of CCAT2." (PMID 27833083, 2016). "The expression of CCAT2 was significantly higher in glioma tissues than in adjacent normal tissues." (PMID 27833083, 2016). "Given that decreased expression of CCAT2 inhibited proliferation in vitro, we validated the in vitro effects of CCAT2 downregulation in vivo by injecting the indicated stable expression glioma cell lines with CCAT2 shRNA or its respective controls into the brains of nude mice." (PMID 27833083, 2016). "Functional assays in vitro and in vivo demonstrated that knockdown of CCAT2 could inhibit proliferation, cell cycle progression and migration of glioma cells." (PMID 27833083, 2016). "Furthermore, transwell assays indicated that the down-regulation of CCAT2 in the glioma cells resulted in a marked decrease in cell migration." (PMID 27833083, 2016). "CCAT2 by disturbing the normal function of miR-424 could enhance resistance in glioma." (PMID 34178658, 2021). "In addition, knockdown of lncRNA CCAT2 inhibited endothelial angiogenesis in glioma." (PMID 34200145, 2021). "Through combining our above results, we speculated that abnormal expression of CCAT2 could inhibited the Wnt/β-catenin pathway by suppressing the downstream genes expression of Wnt/β-catenin signaling pathway in glioma cells, thus play significant roles in glioma origination and development." (PMID 27833083, 2016). "However, the expression and detailed function of CCAT2 in glioma remains largely unknown and needs to be investigated." (PMID 27833083, 2016). "A new regulatory axis between CCAT2/miR-424 and the protein checkpoint kinase 1 (CHK1) gene was described in glioma, with roles in the tumor chemoresistance." (PMID 34830370, 2021). "The overexpression of CCAT2 in HUVECs results in the activation of VEGFA and TGFβ, thereby promoting angiogenesis of glioma cells." (PMID 33912560, 2021). "For instance, knockdown of long noncoding RNA CCAT2 inhibits cellular proliferation, invasion, as well as induces early apoptosis by regulating EMT in glioma cells." (PMID 28199978, 2017). "Thus, our study provides evidence that CCAT2 may function as a potential biomarker for glioma." (PMID 27833083, 2016).
gastric cancer (24 papers, 2016 to 2025). A primary or metastatic malignant neoplasm involving the stomach. "The experimental results suggest that lncRNA CCAT2 upregulates the expression of CD44v6 by binding to ESRP1, thereby mediating the selective splicing of CD44 and promoting the development of gastric cancer, which is associated with shorter patient survival." (PMID 40046628, 2025). "Besides, it is reported that higher CCAT2 expression is strongly linked with the more malignant molecular process in patients with gastric cancer (GC), and silencing CCAT2 prevented GC progression." (PMID 35170195, 2022). "Moreover, CCAT2 expression in gastric cancer modulates the expression of the POU5F1B, a retrogene located adjacent to MYC that inhibits apoptosis and stimulates angiogenesis and metastasis." (PMID 34830370, 2021). "Similarly, lncRNAs, such as H19, TINCR, AOC4P, BANCR, LINC00857, and CCAT2, are detectable in body fluids and can be used to efficiently differentiate gastric cancer patients from healthy controls." (PMID 34885213, 2021). "Knockdown of lncRNA CCAT2 inhibited cell viability and cell cycle, and promoted the apoptosis and autophagy of gastric cancer cells may though blocking mTOR signaling." (PMID 34234860, 2021). "Previous studies showed that CCAT2 overexpression promoted LATS2 expression in gastric cancer cell." (PMID 29502343, 2018). "Colon cancer associated transcript 2 (CCAT2) appears to promote EMT, as lncRNA CCAT2 knockdown leads to increased E-cadherin and decreased vimentin levels in gastric cancer cells and, additionally, CRC cells expressing higher levels of CCAT2 display increased vimentin expression." (PMID 28430163, 2017). "In gastric cancer, CCAT2 was upregulated and used as a potential indicator of prognosis." (PMID 27015551, 2016). "ESRP1 binds to lncRNA CCAT2, which regulates CD44 splicing, promoting the transition from standard CD44 to CD44v6 and facilitating gastric cancer progression." (PMID 40046628, 2025). "In gastric cancer, CCAT2 was investigated as part of a 5 lncRNAs (TINCR, CCAT2, AOC4P, BANCR, and LINC00857) plasma panel." (PMID 34830370, 2021). "The research discovered significant increase of plasma lncRNA (TINCR, CCAT2, AOC4P, BANCR, and LINC00857) in gastric cancer cell lines." (PMID 33473276, 2021). "LncRNA CCAT2 promotes gastric cancer proliferation and invasion through regulating the E-cadherin and LATS2.And LINC00240 promotes GC tumorigenesis via a LINC00240/miR-124-3p/DNMT3B axis as an oncogene, so it may be a potential diagnostic biomarker for GC." (PMID 34422902, 2021).
cervical carcinoma (16 papers, 2016 to 2025). A carcinoma arising from either the exocervical squamous epithelium or the endocervical glandular epithelium. "Besides, colon cancer-associated transcript 2 (CCAT2) could be valuable to monitor the prognosis of cervical cancer (CC) patients, and it will improve the diagnostic efficiency of CC with the combination of CCAT2." (PMID 35812755, 2022). "CCAT2: Upregulated in cervical cancer, CCAT2 regulates the Wnt/β-catenin pathway, promoting invasion and metastasis." (PMID 39912983, 2025). "The serum expression levels of a 3 lncRNA panel, which includes CCAT2, were able to distinguish early-stage cervical cancer patients from normal controls, with an area under the curve of 0.894, 67.1% sensitivity, and 96.1% specificity." (PMID 34830370, 2021). "In cervical cancer patients the high expression of CCAT2 is correlated to advanced FIGO stage, lymph node metastasis, deep cervical invasion and reduced survival." (PMID 32154165, 2020). "CCAT2 has found to be up regulated in HeLa, CaSki, and SiHa cervical cancer cells as well as in cervical cancer tissues." (PMID 32154165, 2020). "The inhibition of CCAT2 expression by siRNA in cervical cancer cells has shown to suppress cell proliferation." (PMID 32154165, 2020). "When CCAT2 expression level is inhibited by transfection of siRNA in cervical cancer cells, it leads to significant suppression of their proliferation and survival." (PMID 28637507, 2017). "There is a correlation between CCAT2 and metastasis which reveals a poor prognosis in patients with cervical cancer." (PMID 28637507, 2017). "However, the molecular mechanism mediating the activity of CCAT2 in cervical cancer remain uncharacterized." (PMID 32154165, 2020). "However, the mechanisms mediating the mode of action of CCAT2 in cervical cancer are still unclear." (PMID 28637507, 2017). "However, the clinical value of CCAT2 in cervical cancer (CC) remains unclear." (PMID 35115025, 2022). "This will be a good idea for the future study of the mechanism between CCAT2 and HPV in cervical cancer." (PMID 35115025, 2022). "LncRNA CCAT2 was also found to be up-regulated in cervical squamous cell cancer tissues, patients with high expression of lncRNA CCAT2 had poor OS and PFS rates and was an independent poor prognostic factor for cervical cancer patients." (PMID 29720427, 2018). "LcnRNAs of HOTAIR, CCAT2, MALAT1, EBIC and MEG3 have been reported to be involvled in cervical cancer metastasis." (PMID 27736969, 2016).
lung carcinoma (14 papers, 2014 to 2025). "Metastasis-associated lung adenocarcinoma transcript 1 (MALAT1) and colon cancer-associated transcript 2 (CCAT2) are acted as biomarkers in patients with lung cancer." (PMID 36357869, 2022). "CCAT2 (colon cancer associated transcript 2) is also a predictive marker for metastasis in lung cancer." (PMID 28672805, 2017). "MALAT-1 and colon cancer-associated transcript 2 (CCAT2) genetic polymorphisms could predict the risk of lung cancer and the response to platinum-based chemotherapy." (PMID 39912974, 2025). "Additionally, CCAT2 genetic polymorphisms were closely related to the susceptibility of lung cancer cells to platinum‐based chemotherapy response; thus, it may be an underlying biomarker for the disease prediction and chemotherapy response." (PMID 35170195, 2022). "LncRNA CCAT2 can promote the proliferation of lung cancer cells by affecting Wnt signaling pathway, lncRNA PinX1 can block the growth of lung cancer cells in G0/G1 phase, thus inhibiting the proliferation of lung cancer and acting as anti-tumor effect." (PMID 33976738, 2021). "Gong et al13 found that SNPs in HOTTIP, H19, and CCAT2 were associated with lung cancer risk, and SNPs in MALAT1, H19, CCAT2, HOTAIR, and ANRIL were related to lung cancer patients’ response to platinum‐based chemotherapy." (PMID 30980423, 2019). "Instead, it appears that copy number alterations in 8q24 occur frequently in lung cancers, suggesting an alternate mechanism other than SNP regulation of the CCAT2 transcript in lung cancer pathogenesis." (PMID 29113413, 2017). "Reduced expression of CCAT2 inhibited lung cancer cell proliferation and invasion." (PMID 29502343, 2018). "We filtrated expression of lncRNAs in lung cancer cells after sevoflurane treatment, namely PCAT6, UCA1, SNHG1, CCAT2, and found that the level of PCAT6 was significantly suppressed after sevoflurane administration." (PMID 33987473, 2020).
ovarian carcinoma (14 papers, 2016 to 2025). A malignant neoplasm originating from the surface ovarian epithelium. "Long non-coding RNA colon cancer-associated transcript 2 (CCAT2) is upregulated in ovarian cancer cells and promotes epithelial-mesenchymal transition (EMT) at least partially through the Wnt/β-catenin pathway." (PMID 33227961, 2020). "The oncogenic long non-coding RNA (lncRNA) CCAT2 (colon cancer associated transcript 2) is overexpressed in ovarian cancer." (PMID 32230936, 2020). "To explore the underlying mechanism of calcitriol regulation of MYC in ovarian cancer cells, we studied the interaction of CCAT2 and TCF4 at the MYC promoter." (PMID 32230936, 2020). "To further explore the role of CCAT2 in ovarian cancer, we next evaluated the associations its gene expression with several clinicopathological features." (PMID 27283598, 2016). "Colon-cancer-associated transcript 2 (CCAT2) is overexpressed in ovarian cancer cells." (PMID 37190145, 2023). "The high expression of CCAT1 and CCAT2 was significantly associated with recurrence-free survival and overall survival in colon cancer, gastric cancer, hepatocellular carcinoma, breast cancer, and ovarian cancers." (PMID 34204094, 2021). "The lncRNA CCAT2 (colon cancer associated transcript 2) was recently shown to be involved in several cancers; however, its role in ovarian cancer remains unknown." (PMID 27283598, 2016). "Interestingly, higher CCAT2 expression levels were associated with a shorter overall survival (P = 0.006) and disease-free survival (P = 0.001) in ovarian cancer patients." (PMID 27283598, 2016). "In addition, higher CCAT2 gene expression level was associated with poor prognosis in ovarian cancer patients." (PMID 27283598, 2016). "Another study showed that CCAT1 regulates miR-490-3p in ovarian cancer, indicating new therapeutic strategies, and then explored CCAT2′s co-expressed genes, suggesting targeting CCAT2 pathways for cancer therapy." (PMID 40861865, 2025). "Gemini curcumin shows suppressing effects on CCAT2, leading to the inhibition of ovarian cancer cell proliferation via the CCAT2–miR-424-5p axis." (PMID 37190145, 2023). "CCAT2 was also found to be highly expressed in pancreatic ductal adenocarcinoma, ovarian cancer tissues and bladder cancer." (PMID 35115025, 2022). "This ceRNA relationship between CCAT2 and miR-424 was first described in epithelial ovarian cancer, where the tumorigenic effects of CCAT2 were found to be modulated via the inhibition of the tumor suppressor activity of the miR-424." (PMID 34830370, 2021). "Inhibition of CCAT2 in ovarian cancer cell lines reduced invasiveness and cellular progression and inhibited EMT by downregulating vimentin and N-cadherin and upregulating E-cadherin." (PMID 34830370, 2021). "Our results provide a novel target, CCAT2, in the mechanism of action of vitamin D. The data strengthen the support of vitamin D as a key nutraceutical to prevent ovarian cancer invasion and metastasis." (PMID 32230936, 2020). "Our in vitro study showed that as low as 100 nM calcitriol can significantly down-regulate CCAT2 and 500 nM calcitriol has obvious anti-growth and anti-invasion effects in ovarian cancer cell lines." (PMID 32230936, 2020). "Since CCAT2 expression is elevated in ovarian cancer and CCAT2 promotes cancer growth and metastasis, we determined the effects of vitamin D on CCAT2 in these cell lines." (PMID 32230936, 2020). "In this study, we found that calcitriol suppressed ovarian cancer cell growth, migration, and invasion by down-regulating lncRNA CCAT2, thus inhibiting its downstream onco-protein c-Myc." (PMID 32230936, 2020). "Of note, 1,25(OH)2D3 inhibits CCAT2 expression in ovarian cancer cells concomitantly with a reduction in cell proliferation, migration, and invasion." (PMID 33227961, 2020). "To determine the role of CCAT2 in calcitriol’s inhibition of c-Myc protein, we used siRNA to specifically knock down CCAT2 in ovarian cancer cells." (PMID 32230936, 2020).